LEP (leptin)
Diseases named in the same sentence as LEP in open-access papers (continued):
Sharing a sentence is not in itself a finding about the gene and the disease.
Insulin resistance (continued). "On the other hand, leptin level was not higher in our patients than in control subjects and its correlation with insulin resistance is weak." (PMID 32089876, 2020). "We were especially interested in evaluating established adipokines such as adiponectin and leptin, as well as novel proinflammatory adipokines, i.e., omentin, chemerin, and MCP-1 were shown to induce insulin resistance, endothelial dysfunction, and systemic inflammation." (PMID 33256114, 2020). "However, this relation between leptin, the PI3K signal pathway and insulin resistance can be involved in other pathologies, such as colorectal cancer." (PMID 31936857, 2020). "Among the various inflammatory mediators, leptin, IL-6 and TNF-α are the major pro-inflammatory mediators that paly their decisive role to induce the inflammatory responses during the pathogenesis of DM and development of insulin resistance." (PMID 31929574, 2020). "Insulin resistance (fasting insulin and HOMA‐index of insulin resistance) in early pregnancy was an important predictor for boys' sum of skinfolds, in addition to fasting glucose and maternal adiposity (leptin, BMI and neck circumference) throughout pregnancy." (PMID 32141687, 2020). "The circulating adiponectin levels were only slightly decreased in the diabetic rats, but the adiponectin/leptin ratio was markedly decreased in all the diabetic rats supplemented with SGs, while insulin resistance indices were not affected by the treatment." (PMID 33396905, 2020). "The plasma leptin/APN ratio is emerging as a marker for metabolic syndrome and insulin resistance." (PMID 32566092, 2020). "Furthermore, serum leptin levels were also significantly higher in MUO compared to MHO, confirming the role of this adipokine in determining insulin resistance and metabolic impairment independently of the age and BMI-z score of the population studied." (PMID 32731619, 2020). "Moreover, BAFF−/− mice showed enhanced leptin and FGF21 production, which provides another explanation for the improving effect of BAFF depletion on insulin resistance." (PMID 32698539, 2020). "Nevertheless, it is noteworthy that all MCD models rather showed significant reductions in weight, concomitant loss in liver mass and cachexia, as well as low serum levels of insulin, fasting glucose, leptin and triglycerides, and a lack of insulin resistance." (PMID 32046285, 2020). "A recent study revealed that leptin to adiponectin ratios in STH-infected individuals was increased following anthelmintic therapy which may in small part, lead to the moderate rise in insulin resistance." (PMID 33042134, 2020). "Taken together, our data obtained from experiments using ob/ob mice suggest that BAFF up-regulation contributes to suppression of non-shivering thermogenic activity and consequent insulin resistance under leptin-depleted condition." (PMID 32698539, 2020). "We created separate Cox regression models (hazard ratios per log-transformed ng/mL of leptin and adiponectin) with and without insulin resistance, HOMA-IR." (PMID 32131811, 2020). "Recently, several studies reported that HOMA-IR has some limitations in predicting insulin resistance in certain populations, therefore two adiponectin-based methods were developed; the HOMA corrected by adiponectin (HOMA-AD) and leptin to Adiponectin ratio (LAR)." (PMID 33680012, 2020). "In addition, adipokines secreted by visceral adipose tissue, such as leptin, adiponectin, and TNF-α, play a key role in the tissue sensitivity to insulin, favoring the onset of insulin resistance and tissue inflammation." (PMID 30944697, 2019). "At baseline, ATX levels were positively associated with body mass index, fat mass, insulin resistance (HOMA‐IR) as well as insulin and leptin levels and negatively with fat‐free mass." (PMID 30821134, 2019). "In patients with and without DM, the leptin-to-adiponectin ratio was a useful indicator to assess insulin resistance and atherosclerotic risks." (PMID 31575927, 2019).
Insulin resistance (continued). "Moreover, ANGPTL-4 presented a negative correlation with BMI, waist circumference, weight, insulin, homeostasis model assessment of insulin resistance index (HOMA index), triglycerides, and leptin, and a positive correlation with FFA and vitamin-D." (PMID 31207920, 2019). "It has been reported that there was a direct correlation between circulating leptin levels and insulin resistance markers, while a negative correlation of adiponectin was found with insulin resistance markers." (PMID 31019978, 2019). "The leptin-to-adiponectin ratio (LAR) is used to assess insulin resistance among type-2 diabetes mellitus patients and healthy individuals, while resistin levels were found to correlate with insulin resistance in septic patients." (PMID 31540528, 2019). "Without a confirmed relationship between leptin and insulin resistance, there is not enough evidence to determine if one particular isoflavone source is more beneficial than the other." (PMID 29601521, 2018). "Therefore, we calculated the relative ratio of leptin/MCP-1 and correlated with insulin resistance/sensitivity indexes as well as with other metabolic parameters." (PMID 29785210, 2018). "Specific cytokines produced by visceral adipose tissue, such as leptin, adiponectin and inflammatory factors including TNF-α and IL-6, might lead to insulin resistance." (PMID 29965999, 2018). "After omentectomy, plasma leptin, insulin, NPY, AGRP, and PMCH levels decreased, which may result a decrease in leptin and insulin resistance." (PMID 29367725, 2018). "In addition, few reports have analyzed insulin resistance and FGF23 while including leptin and ghrelin." (PMID 30228288, 2018). "On the other hand, when the obese PCOS were compared to the obese control, the significant differences were lost between the two groups in BMI, leptin, ghrelin, insulin, HDL-C and HOMA-S, but the differences persisted in all the lipids, in glucose level and insulin resistance." (PMID 30131073, 2018). "In vivo POMC-specific Cacna1e knockdown increased hepatic glucose production and insulin resistance, while body weight, feeding, or leptin-induced suppression of food intake were not changed." (PMID 30304668, 2018). "It is well accepted that increased leptin levels are detected in women with PCOS and that may be correlated with insulin resistance, metabolic disorders and infertility." (PMID 29160594, 2018). "On the basis of this brief description of adipose tissues and their role in insulin resistance, this study aims to determine the main factors that contribute to change in the leptin levels in diabetic and nondiabetic Saudi males." (PMID 28348585, 2017). "In non-obese men, BMI and homeostasis model assessment-insulin resistance (HOMA-IR) and leptin, were the risk factors related to knee OA." (PMID 28212675, 2017). "The causal pathways linking depression with metabolic dysregulation have not been fully elucidated, however elevations in insulin resistance (IR), low grade inflammation and leptin have been repeatedly reported." (PMID 29190710, 2017). "In this regard, we found that male rats displayed an increase in insulin resistance markers (HOMA-IR index and leptin/adiponectin ratio) and of liver TG content with aging, along with an important drop in mRNA levels of insulin and leptin receptors in liver and WAT." (PMID 28744221, 2017). "When grouped by insulin resistance, the groups differed significantly in insulin and leptin, but not glucose or triglycerides." (PMID 28093279, 2017). "Gastric cancer surgery led to decreased ghrelin and leptin and increased PYY and GIP, which might have a role in improving insulin resistance and glucose homeostasis." (PMID 29216250, 2017). "Although not consistently demonstrated, GDM women have lower adiponectin and higher leptin levels compared to non-GDM women and the L/A ratio has been associated with insulin resistance (HOMA-IR) during pregnancy." (PMID 28068986, 2017).
Insulin resistance (continued). "After gastric cancer surgery, ghrelin and leptin levels were decreased and PYY and GIP levels were increased, which may have a role in improving insulin resistance." (PMID 29216250, 2017). "Leptin and insulin resistance in the CNS can also result from overactivation of signal transducer and activator of transcription 3/suppressor of cytokine signaling 3 (STAT3/SOCS3), an intracellular pathway that is activated by leptin." (PMID 28592656, 2017). "The present study suggests that adiponectin and leptin play a role in the development of insulin resistance and diabetes independent of metabolic syndrome." (PMID 28786989, 2017). "Altogether, these results indicate that both young and middle‐aged Sirt2−/− mice do not develop a systemic metabolic syndrome or insulin resistance at baseline, in spite of the noted imbalance of adiponectin and leptin levels." (PMID 28984064, 2017). "In obese volunteers, insulin, the homeostatic model assessment of insulin resistance (HOMA-IR), leptin, the leptin/adiponectin ratio, and pro-inflammatory chemokines growth-related oncogene and macrophage-derived chemokine were significantly higher compared to non-obese submariners." (PMID 26867201, 2016). "Furthermore, we found that leptin plasma concentrations also positively correlated with plasma insulin concentrations and HOMA-IR thus insulin resistance." (PMID 27189377, 2016). "After 6 months of therapy, a negative correlation between TBS and insulin resistance (p = 0.02) and leptin (p = 0.01) and a positive correlation with adiponectin were found (p = 0.01)." (PMID 27293954, 2016). "The adult male offspring exhibited traits related to liver disease development overweight, insulin resistance, high leptin levels and hepatic steatosis but not the female counterpart, proving the possibility of gender-specific expression of leptin." (PMID 27703473, 2016). "Moreover, we detected significant associations of adipocyte IRX3 expression with adiponectin and leptin serum levels and with HOMA-IR as a measure of insulin resistance, which were, however, lost after adjustment for BMI SDS and age." (PMID 27560134, 2016). "When fed with high-fat diet, these mice showed decreased weight gain despite hyperphagia, increased triglyceride levels, liver steatosis, reduced adiponectin and leptin levels and did not develop glucose intolerance or insulin resistance." (PMID 27483259, 2016). "Interestingly isorhamnetin attenuated the serum insulin and leptin levels in DIO mice, indicating an improvement of insulin resistance and leptin resistance." (PMID 26775807, 2016). "In addition to leptin an ever expanding number of adipokines are produced by the adipose tissue eg TNF-α, and IL-6 are known to promote insulin resistance which was corroborated here." (PMID 26061745, 2015). "Cases were also more insulin resistant, as demonstrated by their higher levels of HOMA IR, glucose, insulin and leptin levels (P = 0.002, <0.001, 0.005, 0.007, respectively) and by their lower values of Gutt index and adiponectin levels (P = 0.006, 0.002, respectively)." (PMID 25973943, 2015). "The risks of type 2 diabetes, early IGT, and insulin resistance were perfectly predicted by comparing fasting glucose levels to the estimated Matsuda Index 3 (fasting levels of 10- and 12-(Z,E)-HODE/linoleic acids, insulin, and leptin/adiponectin)." (PMID 26132231, 2015). "The results demonstrated that insulin resistance (HOMA-IR) is not a significant predictor of leptin and sOB-R in PCOS subjects with beta unstandardized coefficients of −1.716 and −1.267 and p values of 0.287 and 0.084, respectively." (PMID 26180527, 2015). "Further studies are needed to confirm whether IP-10 collaborates with leptin in the pathogenesis of NAFLD, insulin resistance and the development of incident diabetes." (PMID 25961500, 2015).
Insulin resistance (continued). "Additionally, leptin, insulin, and homeostasis model assessment (HOMA) index were analyzed in obese and normal-weight girls in order to determine the degree of insulin resistance." (PMID 25892992, 2015). "They confirmed a positive correlation between fasting leptin level and insulin resistance independent of body fat mass." (PMID 26693410, 2015). "Serum leptin levels are correlated positively with insulin resistance, independent of body weight or adiposity, both in normoglycemic and in diabetic patients." (PMID 25885799, 2015). "Of note, when insulin resistance index (HOMA-IR) as well as serum insulin, leptin and adiponectin levels were compared in EC patients, it was found that SO and MHO groups can be most effectively distinguished by HOMA-IR value and the ratio of leptin/adiponectin in serum." (PMID 28031919, 2015). "Third, the serum insulin and leptin level, hepatic and peripheral insulin resistance were not measured in the current study." (PMID 24598574, 2014). "Leptin leads to increased levels of several proinflammatory cytokines and the lack of its activity leads to insulin resistance." (PMID 25105135, 2014). "Besides, UA treatment significantly alleviated HFD-induced insulin resistance by lowering insulin level and improving insulin resistance index (HOMA-IR), and decreasing leptin and elevating adiponectin levels in serum." (PMID 24489777, 2014). "Obese adolescents without insulin resistance showed higher and lower circulating levels of leptin and adiponectin, respectively, along with increased plasmatic concentrations of insulin and triglycerides." (PMID 24795698, 2014). "In another study, leptin showed significant positive correlation with parameters of insulin resistance and with triglycerides and strong negative correlation with HDL-cholesterol." (PMID 24741591, 2014). "In the diabetic group adiponectin correlated positively with serum glucose, negatively with serum proinsulin and HOMA beta cell function (P = 0.03) respectively and serum ghrelin (P = 0.003), but not with BMI, HOMA insulin resistance, insulin or leptin." (PMID 23497407, 2013). "The authors inferred that leptin reduction is a reflection of decreased fat accretion, and changes in TNF-α could be evidence of altered insulin resistance." (PMID 23691290, 2013). "We investigated adiponectin, leptin, and TNF-α and assessed the contribution of these molecules to insulin resistance in south Asians.Hypothesis." (PMID 23671875, 2013). "Studies in animal model showed that exogenous leptin administration leads to a dramatic improvement in insulin resistance that is independent of decreased caloric intake." (PMID 23762871, 2013). "The presence of similar abnormalities in AD brains suggests that leptin and PYY levels could also serve as indices of brain insulin resistance." (PMID 25035815, 2013). "Plasma levels of leptin in pregnant women are 2- to 3-fold above nonpregnant levels and result from an upregulation of adipocyte synthesis in the presence of insulin resistance and hyperinsulinemia." (PMID 23691290, 2013). "After controlling for potential confounders, we found that participants with insulin resistance had significantly higher leptin levels compared to those without the condition, at all levels of adiposity, measured by BMI or waist circumference." (PMID 23349940, 2013). "Studies have reported strong evidence that suggests YKL-40, α-HB, soluble CD36, leptin, resistin, IL-18, RBP4, and chemerin could be new biomarkers for the pathogenesis of insulin resistance and endothelial dysfunction in T2DM patients." (PMID 24282409, 2013). "Moreover, the progressive development of insulin resistance during pregnancy is due, in part, to placental cytokines such as TNF-α and leptin." (PMID 23805905, 2013). "In the current study, the individuals with the high ratio of adiponectin/leptin had less dyslipidemia and insulin resistance than those with the low ratio, but they were not free of other risk factors." (PMID 23533722, 2013).
Insulin resistance (continued). "The leptin level was almost double among the insulin resistance group compared to those without the condition." (PMID 23349940, 2013). "As previously reported, Irs2-deficient mice displayed elevated levels of both insulin and leptin until the onset of frank diabetes when beta cells are no longer able to compensate for peripheral insulin resistance." (PMID 23741292, 2013). "While this is indeed a possibility, our more recent findings that the rapid reversal of diet-induced insulin resistance does not require the restoration of response to either leptin or adiponectin challenges this belief." (PMID 23284930, 2012). "Evaluate the effect of physical training on BMI, lipid profile, CRP, leptin and insulin resistance among obese Egyptian children with and without metabolic syndrome." (PMID 22691465, 2012). "Adipose tissue contributes to the generation of this adverse profile and the increased synthesis of cytokines seems to be related with the activation of leptin signaling and independent of insulin resistance in both fat depots." (PMID 23056516, 2012). "In fact, high leptin levels affect insulin binding to its receptor and reduce IRS-1/2 intracellular mediators downstream, thereby potentiating and perpetuating overall insulin resistance." (PMID 23091482, 2012). "We found that both types of RYR (1P-DU and 3P-D1) improved insulin resistance and significantly decreased serum leptin levels without significant changes in weight compared to the control." (PMID 23320041, 2012). "Intracerebroventricular administration of saturated fatty acid palmitate did not elicit leptin or insulin resistance and did not increase hypothalamic inflammatory cytokines." (PMID 22035457, 2011). "• Insulin resistance is further predicted by IL6, leptin and adiponectin." (PMID 19087258, 2008). "In our study we determined for first time the insulin resistance in a sizeable cohort of CHB and CHC patients as one could hypothesize an interaction between insulin resistance and leptin regarding their actions in liver fibrogenesis." (PMID 17540037, 2007). "Lichnovska and her colleagues in their recent report mentioned the significant role of serum leptin in the progression of insulin resistance, but this was not confirmed in the present study." (PMID 17617917, 2007). "Ablation of PPARg2 under conditions of positive energy balance determined by absence of leptin produced early development of severe insulin resistance, β-cell failure, diabetes, and hyperlipidaemia." (PMID 17465682, 2007). "In addition, the A/L ratio is a more effective parameter for insulin resistance than adiponectin or leptin levels alone in nonhyperglycemic individuals." (PMID 40821649, 2025). "Thus, the combined dysregulation of ghrelin, leptin, and AMPK, together with impaired communication via gap junctions, promotes the shift in macrophages from the M2 to the M1 phenotype, thereby favoring insulin resistance." (PMID 41374016, 2025). "ZAG, in turn, is recognized as an anti-inflammatory adipokine that protects against inflammation, showing a strong negative correlation with insulin resistance and leptin secretion while stimulating the production of the anti-inflammatory adipokine adiponectin." (PMID 40564902, 2025). "These promote chronic low‐grade inflammation, insulin resistance, and hyperinsulinemia, which enhance colonic epithelial proliferation and adenoma formation via pathways like IGF‐1 signaling and adipokine dysregulation (e.g., elevated leptin and reduced adiponectin)." (PMID 41332918, 2025). "Finally, the contribution of pandemic-related stress to childhood obesity should be emphasized, as it negatively influences hormonal homeostasis (reduction in leptin, increase in ghrelin), the HPA axis and the intestinal microbiota, favoring dysbiosis and insulin resistance." (PMID 40559430, 2025). "Leptin, adiponectin, and insulin resistance differed based on BMI, but not on GDM status." (PMID 41202005, 2025).